LOXL2 (lysyl oxidase like 2)
Description:
Mediates the post-translational oxidative deamination of lysine residues on target proteins leading to the formation of deaminated lysine (allysine). Acts as a transcription corepressor and specifically mediates deamination of trimethylated 'Lys-4' of histone H3 (H3K4me3), a specific tag for epigenetic transcriptional activation. Shows no activity against histone H3 when it is trimethylated on 'Lys-9' (H3K9me3) or 'Lys-27' (H3K27me3) or when 'Lys-4' is monomethylated (H3K4me1) or dimethylated (H3K4me2). Also mediates deamination of methylated TAF10, a member of the transcription factor IID (TFIID) complex, which induces release of TAF10 from promoters, leading to inhibition of TFIID-dependent transcription. LOXL2-mediated deamination of TAF10 results in transcriptional repression of genes required for embryonic stem cell pluripotency including POU5F1/OCT4, NANOG, KLF4 and SOX2 (By similarity). Involved in epithelial to mesenchymal transition (EMT) via interaction with SNAI1 and participates in repression of E-cadherin CDH1, probably by mediating deamination of histone H3. During EMT, involved with SNAI1 in negatively regulating pericentromeric heterochromatin transcription. SNAI1 recruits LOXL2 to pericentromeric regions to oxidize histone H3 and repress transcription which leads to release of heterochromatin component CBX5/HP1A, enabling chromatin reorganization and acquisition of mesenchymal traits. Interacts with the endoplasmic reticulum protein HSPA5 which activates the IRE1-XBP1 pathway of the unfolded protein response, leading to expression of several transcription factors involved in EMT and subsequent EMT induction. Involved in E-cadherin repression following hypoxia, a hallmark of EMT believed to amplify tumor aggressiveness, suggesting that it may play a role in tumor progression. When secreted into the extracellular matrix, promotes cross-linking of extracellular matrix proteins by mediating oxidative deamination of peptidyl lysine residues in precursors to fibrous collagen and elastin. Acts as a regulator of sprouting angiogenesis, probably via collagen IV scaffolding. Acts as a regulator of chondrocyte differentiation, probably by regulating expression of factors that control chondrocyte differentiation (By similarity).
Synonyms: WS9-14; LOR; LOR2
Tractability: Small molecule: a drug acting on it is in phase 2 or 3 trials; a high-quality ligand is known. Antibody: a drug acting on it is in phase 2 or 3 trials; UniProt places it where antibodies can reach, with high confidence; UniProt predicts a signal peptide or a membrane-spanning region; its Gene Ontology location is reachable by antibodies, with medium confidence. PROTAC: ubiquitination databases record sites on it; a small molecule that binds it is known.
Target class: Enzyme; Oxidoreductase
Gene: Protein-coding gene on chromosome 8 (23,296,897 to 23,425,328, reverse strand). Ensembl gene ENSG00000134013.
Subcellular location: Secreted, extracellular space, extracellular matrix, basement membrane; Nucleus; Chromosome; Endoplasmic reticulum
Subcellular location (Human Protein Atlas): Nucleoplasm; Predicted to be secreted
Pathways (Reactome):
Extracellular matrix organization: Crosslinking of collagen fibrils; Elastic fibre formation
Gene Ontology:
Molecular function: calcium ion binding; copper ion binding; oligosaccharide binding; protein binding; protein-lysine 6-oxidase activity; oxidoreductase activity, acting on the CH-NH2 group of donors, oxygen as acceptor
Biological process: collagen fibril organization; endothelial cell migration; endothelial cell proliferation; epithelial to mesenchymal transition; heterochromatin organization; negative regulation of DNA-templated transcription; negative regulation of transcription by RNA polymerase II; peptidyl-lysine oxidation; positive regulation of epithelial to mesenchymal transition; protein modification process; response to copper ion; sprouting angiogenesis; negative regulation of stem cell population maintenance; positive regulation of chondrocyte differentiation; response to hypoxia
Cellular component: chromatin; chromosome; endoplasmic reticulum; extracellular matrix; extracellular region; nucleoplasm; nucleus; basement membrane; elastic fiber; membrane
Genetic constraint (gnomAD): Loss-of-function variants: 64 observed, 87.67 expected, observed/expected ratio (o/e) 0.73, 90% interval 0.6 to 0.9. The upper end of that interval is the gene's LOEUF score, 0.9, which puts it in group 3 of 6, group 1 being the genes least tolerant of losing a copy. Missense variants: 940 observed, 1,049.7 expected, observed/expected ratio (o/e) 0.9, 90% interval 0.85 to 0.94. Synonymous variants: 429 observed, 415.37 expected, observed/expected ratio (o/e) 1.03, 90% interval 0.95 to 1.12.
Homologues: Orthologues: macaque LOXL2 (99% identical), chimpanzee LOXL2 (92% identical), pig LOXL2 (92% identical), dog LOXL2 (90% identical), rabbit LOXL2 (90% identical), rat Loxl2 (87% identical), guinea pig LOXL2 (87% identical), mouse Loxl2 (86% identical), tropical clawed frog loxl2 (72% identical), zebrafish loxl2b (69% identical), Drosophila melanogaster Loxl1 (19% identical). Paralogues in human: LOXL3 (54% identical), LOXL4 (53% identical), DMBT1 (27% identical), CD163 (25% identical), CD163L1 (25% identical), SSC5D (23% identical), PRSS12 (22% identical), SCART1 (21% identical), LOXL1 (20% identical), LOX (18% identical), SSC4D (14% identical), CD5 (12% identical), and 3 more.
Diseases named in the same sentence as LOXL2 in open-access papers:
LOXL2 is named in the same sentence as 192 diseases in open-access papers, as found by Europe PMC text mining. Sharing a sentence is not in itself a finding about the gene and the disease. The quoted sentences say what the papers report.
breast carcinoma (116 papers, 2008 to 2025). "Inhibiting lysyl oxidase-like 2 (LOXL2), which is associated with poor prognosis, can also reduce breast cancer invasion and ECM deposition." (PMID 40890855, 2025). "High levels of LOXL2 are associated with aggressive breast cancer by reducing cell adhesion and promoting EMT." (PMID 38662225, 2024). "Despite these findings, the exact mechanisms underlying the pro-metastatic and invasive functions of LOXL2 in breast cancer are not fully understood." (PMID 39247609, 2024). "LOXL2 overexpression is not only associated with tumor progression and metastasis but is also an independent prognostic marker in breast cancer patients." (PMID 38672570, 2024). "Our previous studies in a large series of human tumor samples demonstrated that intracellular LOXL2 is associated with poor prognosis in laryngeal squamous-cell carcinomas and with distant metastasis in basal-like breast carcinomas." (PMID 37298909, 2023). "LOXL2 up-regulation is associated with the metastasis of cancer such as colon cancer and breast cancer, through regulating the EMT phenotype." (PMID 36830091, 2023). "In recent years, more and more studies have confirmed its upregulated expression in breast cancer, liver cancer, gastric cancer, lung cancer, etc., in which LOXL2 plays a pivotal role in TME by promoting tumor-associated fibrosis and tumor angiogenesis." (PMID 36293126, 2022). "It is first reported that LOXL2 promotes tumor progression and is associated with poor prognosis in breast cancer." (PMID 35126449, 2021). "Secreted LOXL2 promotes collagen I fiber crosslinking and affects matrix remodeling, which has been linked to increased metastatic capability in breast cancer." (PMID 34011405, 2021). "Immunohistochemical studies demonstrated that approximately 60% of basal breast carcinomas have increased intracellular LOXL2 with perinuclear distribution, associated with mRNA overexpression." (PMID 33669630, 2021). "We imputed expressions of seven genes other than TBX1 and LOXL2 and showed that these genes were associated with breast cancer risk in either the ABCC or BCAC data at P < 0.05." (PMID 32139696, 2020). "In breast cancer patients, LOXL2 expression is associated with invasiveness and negatively influences survival, acting as a key driver of lung metastasis." (PMID 31130685, 2019). "Cytoplasmic/perinuclear localization is associated with distant metastasis of breast cancer cell line, while nuclear LOXL2 has a role in epithelial-to-mesenchymal transition." (PMID 28764769, 2017). "The inhibition of LOXL2 with shRNA caused a mesenchymal-to-epithelial transition in breast cancer cells and a reduced invasive phenotype; these effects were then reversed using recombinant RAMP3." (PMID 28845385, 2017). "Accordingly, up-regulation of LOXL2 has been observed in breast cancer where high levels of LOXL2 have been associated with more aggressive phenotype and metastatic potential." (PMID 27655685, 2016). "Increased expression of LOXL2, a member of the lysyl oxidase family, has previously been shown in colon- and esophageal cancer, and it has also been associated with breast cancer tumor grade." (PMID 18522746, 2008). "Notably, increased LOXL2 expression is significantly linked to a reduced disease-free survival (DFS) period in patients with breast cancer (p < 0.01)." (PMID 39247609, 2024). "Consequently, high LOXL2 expression is considered a significant risk factor for the early development of breast cancer metastasis." (PMID 39247609, 2024). "In addition, LOXL2 expression in breast cancer cells has been associated with a more aggressive phenotype and enhanced metastatic potential." (PMID 31817646, 2019). "In addition, high LOXL2 protein expression has been found to associate with poorer overall survival in gastric cancer, laryngeal squamous cell carcinoma, and breast cancer." (PMID 30701028, 2018).
breast carcinoma (continued). "Furthermore, increase in LOXL2 expression was associated with significant decrease in RFS of the breast cancer patients." (PMID 27655685, 2016). "Hence, these findings demonstrate that breast cancer patients with increased LOXL2 expression have a higher risk to develop recurrence of the disease, and increase in LOXL2 expression is associated with increase in EMT/CSC like markers." (PMID 27655685, 2016). "Using mass spectrometry we identified two precursor proteins Galectin 3 binding protein (G3BP) and Lysyl oxidase 2-like protein (LOXL2) that associate with eHsp90 in MDA-MB231 breast cancer cell conditioned media and confirmed that LOXL2 binds to eHsp90 in immunoprecipitates." (PMID 24785146, 2014). "In breast cancer, LOXL2‐activated PEAR1 phosphorylation facilitates metastasis by maintaining CD44 stability." (PMID 41395115, 2025). "Immunohistochemistry (IHC) depicted elevated levels of LOXL2 in fulvestrant‐resistant breast cancer organoids compared to fulvestrant‐sensitive organoids, with no significant variance in LOX expression." (PMID 40179101, 2025). "The purpose of this study was to characterise the immunohistochemical expression of LOX and LOXL2 in canine mammary carcinomas and to investigate their prognostic significance." (PMID 41408914, 2025). "Our results suggest that lysyl oxidases such as LOXL2 are potential prognostic markers in mammary carcinomas of dogs." (PMID 41408914, 2025). "Knockdown of the LOXL2 gene has been shown to mitigate lung metastasis in breast cancer cells, whereas overexpression of LOXL2 enhances lung metastasis by upregulating Snail1." (PMID 39247609, 2024). "Compared to healthy controls, LOXL2 levels are significantly elevated (2.18-fold) in serum from patients with breast cancer." (PMID 39247609, 2024). "In conclusion, LOXL2 is highly expressed in breast cancer, serving as a potential prognostic indicator, and promoting breast cancer cell growth, proliferation, migration, and invasion." (PMID 39247609, 2024). "High cytoplasmic/perinuclear LOXL2 expression is clearly detected in human basal-like breast cancer (BLBC) patients." (PMID 39247609, 2024). "LOXL2 is crucial for breast cancer lung metastasis because it promotes dedifferentiation, tumour invasion, and metastasis." (PMID 39247609, 2024). "Nevertheless, research on LOXL2 has suggested that both its intracellular and extracellular forms play a role in the progression of breast cancer." (PMID 39247609, 2024). "Treatment with neutralizing antibodies against LOXL2 has been shown to significantly reduce the metastatic potential of breast cancer cells." (PMID 39247609, 2024). "Overexpression of LOXL2 in noninvasive breast cancer cells induces tumour fibrosis and enhances invasiveness." (PMID 39247609, 2024). "Intriguingly, these interventions do not impede the growth of primary tumours, underscoring the pivotal role of LOXL2 in the metastatic cascade of breast cancer." (PMID 39247609, 2024). "In vitro proliferation, migration, and invasion experiments using the MDA-MB-231 triple-negative human breast cancer model were used to evaluate the effectiveness of these LOXL2 inhibitors." (PMID 38672570, 2024). "Secreted LOXL2 from breast cancer cells activates stromal fibroblasts in the tumour microenvironment through integrin-induced FAK signalling." (PMID 39247609, 2024). "It was reported that tumor-secreted LOXL-2 activated fibroblast through FAK signaling in breast cancer." (PMID 38291516, 2024). "LOXL2 interacts with extracellular heat shock protein HSP90 in breast cancer and glioma cell lines, although the functional significance of this interaction remains to be elucidated." (PMID 37762708, 2023). "LOXL2 level has been reported to correlate with poor prognosis of several solid cancers, such as breast cancer 16, colon cancer 17, and gastric cancer." (PMID 37056396, 2023).
breast carcinoma (continued). "OSM signaling also leads to TME remodeling in breast cancer as OSM induces the expression of lysyl-oxidase like 2 (LOXL2), which leads to crosslinking and alignment of collagen I fibers present in the stromal ECM." (PMID 37841259, 2023). "This approach uncovered levoleucovorin as an efficient and stable LOXL2 inhibitor that exhibits antiproliferative efficacy in two breast cancer cell lines." (PMID 37762708, 2023). "While overexpression of LOXL2 increases lung metastasis possibly via SNAIL1 upregulation in breast cancer." (PMID 36906534, 2023). "Escin Ia inhibits the invasion and migration of MDA-MB-231 breast cancer cells through selective downregulation of LOXL2 expression and prevents the EMT process." (PMID 37762708, 2023). "The high expression of the lysyl oxidase-like 2 (LOXL2) gene is closely associated with the high invasiveness of tumors and the metastasis and prognosis of female breast cancer." (PMID 37427098, 2023). "LOXL2 is highly expressed in aggressive tumor types and plays a key role in promoting breast cancer metastasis." (PMID 37937685, 2023). "For example, breast cancer and oral squamous cell carcinoma syngeneic models have provided mechanistic insights into the molecular action of Loxl2 in tumour progression and metastasis." (PMID 37762708, 2023). "It has been demonstrated that, in breast cancer, LOXL2 promotes angiogenesis through the activation of the AKT-SNAI1 and ERK pathways." (PMID 36454513, 2023). "Among them, LOXL2 has been shown to be upregulated and contribute to the invasion and metastasis of several cancers, including breast cancer." (PMID 37958410, 2023). "The analysis of the gene expression profile of breast cancer cells silenced for LOXL2 revealed 120 DEGs involved in EMT." (PMID 37298909, 2023). "Loxl2 deletion in mammary tumour cells dramatically decreased lung metastasis, while Loxl2 overexpression promoted metastatic tumour growth of MMTV-PyMT-breast tumours." (PMID 37762708, 2023). "Plenty of studies have revealed that LOXL2 participated in tumor progression, metastasis, poor prognosis and chemoradiotherapy resistance in varied cancers, e.g., lung cancer, breast cancer, pancreatic cancer and colorectal cancer." (PMID 36185284, 2022). "In breast carcinoma cells, enzymatically inactive LOXL2 was found to induce EMT via alternate means." (PMID 36232685, 2022). "In the clinical trial of treating breast cancer patients with copper ion chelators, the level of LOXL2 was reduced." (PMID 36699089, 2022). "Several authors have proposed the LOX family proteins, mostly LOXL2 as therapeutic targets in breast cancer treatment, in accordance with the data presented here." (PMID 35800439, 2022). "The lysyl oxidase‐like protein LOXL2 promotes lung metastasis in breast cancer via premetastatic niche formation." (PMID 34981672, 2022). "Regarding cancer, LOX and LOXL2 contribute to breast cancer metastasis, and LOXL2 is involved in the initiation and progression of head and neck squamous cell carcinoma." (PMID 35267510, 2022). "LOXL2 stimulates the proliferation of breast cancer cells and contributes to their oncogenic transformation and pathogenesis, suggesting that the development of LOXL2 inhibitors is an effective therapeutic strategy." (PMID 35976950, 2022). "In this study, the biosensor was able to distinguish high LOXL2 in urine samples from patients with breast cancer compared to control samples." (PMID 33513979, 2021). "Tumour cell-derived lysyl oxidase-like protein 2 (LOXL2) was investigated by immunohistochemistry in tissues from breast cancer patients." (PMID 34833492, 2021). "In this review, we describe LOX enzymes and their role in promoting cancer development and metastases, with a special focus on LOXL2 and breast cancer progression." (PMID 33669630, 2021).